INS (insulin)
Diseases named in the same sentence as INS in open-access papers (continued):
Sharing a sentence is not in itself a finding about the gene and the disease.
diabetes (continued). "Recent data identify altered ER redox homeostasis as a critical mechanism that contributes to insulin granule loss in diabetes." (PMID 38935435, 2024). "It results from a deficiency of insulin production in type 1 diabetes mellitus (T1DM) or an inability to utilize this hormone as occurs in type 2 diabetes (T2D)." (PMID 38281991, 2024). "Regulation of glucose levels during insulin-evoked hypoglycemia is impaired in patients with diabetes and can lead to a condition called hypoglycemia-associated autonomic failure (HAAF)." (PMID 39487352, 2024). "Increased levels of fasting insulin increase the risk of pre-diabetes in women and physical activity is known to enhance the maternal insulin sensitivity thereby decreasing the need for insulin." (PMID 38977979, 2024). "Diabetes is also associated with profound disturbances in fat metabolism, as insulin is the primary fat-storage hormone." (PMID 39763617, 2024). "Enhancing β-cell insulin secretion capacity remains a critical challenge in the reversal of β-cell dysfunction and/or loss in diabetes." (PMID 38704026, 2024). "Type 2 diabetes mellitus (T2DM) is a heterogeneous disease caused by insulin resistance (IR) and insufficient insulin secretion, accounting for about 90–95% of all diabetes mellitus." (PMID 38890991, 2024). "Regarding insulin sensitivity, some epidemiological studies have observed an association between greater coffee consumption and a lower incidence of type 2 diabetes mellitus." (PMID 39275165, 2024). "Associations between HbA1c and diabetes duration with the difference in Euclidian distance persisted even after further adjustments for insulin and metformin use." (PMID 39027659, 2024). "Coordinated activity disruptions in these multicellular networks contribute to irregular insulin secretion, a hallmark of diabetes." (PMID 38739680, 2024). "Diabetes mellitus is a chronic metabolic and endocrine disorder characterized by anomalies in protein, lipid, and carbohydrate metabolism caused by deficits in insulin action or production." (PMID 38654804, 2024). "In univariate analysis, risk factors included BDI score ≥ 11, HAM-D score ≥ 8, diabetes on insulin, anticoagulant use, atrial fibrillation, and serum creatinine level ≥ 130 μmol/L." (PMID 39598055, 2024). "Named type 1 due to its similarity to type 1 diabetes mellitus, both conditions exhibit reduced insulin concentration in the blood, although the causes differ." (PMID 38473200, 2024). "As such, the American Diabetes Association (ADA) guideline recommends a basal-bolus regimen in the postoperative ward in favour of sliding-scale insulin only." (PMID 39099754, 2024). "Disruptions in this coordination are implicated in irregular insulin secretion, a hallmark of diabetes." (PMID 38739680, 2024). "Diabetes is a chronic metabolic disease characterized by hyperglycemia, deficient insulin secretion, or insulin resistance." (PMID 38396842, 2024). "In C. elegans, motivation to forage for food is regulated by insulin signaling, which is significant because defective insulin signaling in humans is not only associated with diabetes mellitus, but also apathy, depression and suicide." (PMID 38362034, 2024). "A prevalence of 40% mutations of known diabetes genes in the subgroup with low insulin secretion suggests that at least 1.7% of patients with adolescent obesity have monogenic diabetes." (PMID 38550917, 2024). "DPP-4 inhibitors are used to treat patients with type 2 diabetes mellitus in order to extend the half-life of incretins, as active incretins cause pancreatic β cells to secrete insulin." (PMID 38337597, 2024). "Risk factors implicated across various populations and diabetes types include obesity, hypertension, longer diabetes duration, insulin therapy, neuropathy, nephropathy, and dyslipidemia." (PMID 39001254, 2024). "Lowering insulin below a critical threshold causes diabetes, but elevated insulin is also associated with detrimental changes." (PMID 38131197, 2024).
diabetes (continued). "Type 2 diabetes is a type of diabetes mainly caused by insulin resistance or accompanied by insufficient insulin secretion for various reasons, accounting for more than 90% of diabetes patients." (PMID 38784180, 2024). "Btk deficiency in NOD mice alters peripheral B cell subsets, impairs B cell proliferation and insulin autoantibody production, and protects against T1D, whereas the introduction of insulin-specific VH125Tg into Btk-deficient NOD mice restored diabetes." (PMID 38651407, 2024). "Diabetes mellitus is a prevalent metabolic disorder with multiple causes resulting from insufficient insulin secretion or defective insulin action." (PMID 39055491, 2024). "Patients with autoimmune diabetes mellitus need a lifetime replacement with exogenous insulin, and the maintenance of adequate glycemic control is considered essential for limiting the risk of diabetes-related acute and chronic complications." (PMID 38743078, 2024). "Understanding the insulin–heart axis is crucial for developing therapeutic strategies to mitigate the cardiovascular complications associated with insulin resistance and diabetes." (PMID 39125938, 2024). "The accumulation of iron has been linked to heightened oxidative stress and can disrupt insulin secretion, potentially increasing the risk of developing diabetes and cardiovascular disease (CVD)." (PMID 39179569, 2024). "Diabetes is a chronic disease in metabolic disorders, and its pathological features are impaired insulin secretion or biological dysfunction, or both, which causes elevated blood sugar levels, whereas obesity is a high-risk factor for diabetes." (PMID 38339168, 2024). "Inflammatory reactions, sensitivity to insulin, the breakdown of lipids, and complications associated with diabetes are all influenced by the Hh signaling system." (PMID 39061964, 2024). "Studies have indicated its potential in improving insulin sensitivity and glucose metabolism, which are crucial factors in mitigating the risk of developing type 2 diabetes mellitus." (PMID 39723066, 2024). "An inadequate expansion of β cell mass to compensate for increased insulin demand, followed by the eventual loss of β cells due to apoptosis, is a hallmark of diabetes." (PMID 38811543, 2024). "Diabetes mellitus (DM) is a chronic systemic metabolic disorder caused by a relative or absolute deficiency of insulin secretion and dysfunction of insulin action and mainly manifests as elevated blood glucose." (PMID 38520616, 2024). "White blood cells significantly mediated the associations between diabetes-related markers (glycohemoglobin, fasting glucose, and insulin) with OAB, and the proportions were 7.23%, 8.08%, and 17.74%, respectively (all p < 0.0001)." (PMID 38745959, 2024). "GDM is considered a state of pre-diabetes where there is glucose intolerance due to deficiency of insulin secretion or chronic insulin resistance at cellular level which probably would have occurred even before the pregnancy." (PMID 38977979, 2024). "Insulin errors in hospital still occur frequently for inpatients with diabetes, putting them at risk of severe harm and negatively impacting their inpatient experience." (PMID 39666732, 2024). "Apart from insulin, other hormones, such as adiponectin, have been implicated in diabetes, particularly type 2 DM." (PMID 39091901, 2024). "Overall, MR-409’s ability to protect and enhance the function of β-cells addresses two key issues in diabetes: the loss of β cells and the impairment of insulin secretion, thereby helping to maintain glucose homeostasis." (PMID 39560873, 2024). "A similar drop in glucose-stimulated [Ca2+]i dynamics coordination has been described in vitro in islets from mouse models of diabetes and from humans with type 2 diabetes, being associated with abnormal insulin secretion oscillatory patterns." (PMID 38814444, 2024).
diabetes (continued). "The first involves higher adiposity in subcutaneous tissues (abdomen and thigh), lower liver fat, improved insulin sensitivity, and decreased risk of cardiometabolic diseases and diabetes complications." (PMID 38530928, 2024). "The control of cardiovascular risk factors in patients with type 2 diabetes mellitus is essential for improving insulin sensitivity." (PMID 39456481, 2024). "Insulin, particularly due to its pivotal association with diabetes, assumes a central role within the system." (PMID 38534414, 2024). "In this retrospective cohort review, we found patients with head and neck cancer who have pre-existing type 2 diabetes requiring insulin at baseline have a high risk of severe diabetes-related complications while receiving CCRT." (PMID 38392055, 2024). "The most common predisposing factor is treatment with protamine-containing insulin in patients with diabetes mellitus." (PMID 39421103, 2024). "The TCF7L2 gene, known to influence pancreatic β-cell function and insulin secretion, plays a significant role in glucose homeostasis, making it a crucial genetic marker in the context of diabetes risk." (PMID 39469345, 2024). "Insulin resistance, a key characteristic of type 2 diabetes mellitus, has been linked to vitamin D, as studies suggest its involvement in regulating insulin sensitivity." (PMID 39463653, 2024). "It leads to pancreatic damage and causes diabetes by reprogramming cells to produce more glucagon and less insulin." (PMID 39099965, 2024). "Prior to adjustments, share of support staff with diabetes course related a higher risk of attaining HbA1c <7.0% (53 mmol/mol) after basal insulin-initiation (OR = 1.84, [95%CI, 1.10, 3.36]), but after adjustment, this was no longer statistically significant." (PMID 38116986, 2024). "Another possible mechanism of action of Elo in cardiac dysfunction associated with diabetes is through the modulation of genes that encode insulin signaling." (PMID 39055210, 2024). "Patients treating their diabetes with diet and exercise, oral medication, or continuous glucose monitoring weren’t considered high risk since their glucose monitoring, or insulin injection exposure was less." (PMID 39423235, 2024). "Diabetes mellitus (DM) is a chronic, metabolic disease caused by defects in insulin function, insulin discharge, or both, which eventually results in increased blood glucose levels." (PMID 38338237, 2024). "We found the white blood cells significantly mediated the associations between diabetes-related markers (glycohemoglobin, fasting glucose, and insulin) and OAB, and the proportions were 7.23%, 8.08%, and 17.74%, respectively." (PMID 38745959, 2024). "Several previous studies have demonstrated significant strain-specific differences in mice regarding insulin release, pancreas size and structure, and susceptibility to diabetes." (PMID 38358819, 2024). "Glucose is known to cause intolerance, decrease insulin sensitivity, and potentially lead to hyperinsulinemia or diabetes." (PMID 38256692, 2024). "Insulin, a 5.8 kDa peptide hormone composed of two disulfide-linked chains (A and B), is a widely-used, essential therapeutic for individuals with diabetes mellitus." (PMID 38703998, 2024). "The PI3K/AKT and MAPK signaling pathways can be compromised in people with diabetes, which can cause enhanced hepatic glucose production and decreased insulin sensitivity, implying a major role for these substrates in maintaining glucose balance." (PMID 38674437, 2024). "Diabetes mellitus (DM) is a long-term metabolic condition that is caused by high blood glucose levels, insulin malfunction, and insulin deficiency." (PMID 39776729, 2024). "Across all four models, total glucose AUCs from the MMTT were each independently associated with an increased risk of diabetes even after adjustment for insulin action and secretion." (PMID 38987291, 2024).
diabetes (continued). "This type of diabetes is associated with a slower decline in insulin production compared with T1DM and develops more frequently in individuals older than 30 years." (PMID 39529980, 2024). "The quality of marriage was found to affect health-related QoL and disease adaptation in a survey conducted by the American Diabetes Association to assess the impact of marital status on glucose control in insulin-treated diabetics." (PMID 38500939, 2024). "Hypopituitarism is also associated with reduced insulin sensitivity and an increased prevalence of type 2 diabetes mellitus, particularly in women." (PMID 39370498, 2024). "A study showed that sleep deprivation, along with CR disruption, can lead to insufficient insulin secretion and increased blood glucose levels, which significantly increases the risk of obesity and diabetes." (PMID 39716153, 2024). "These elements cause a reduction in insulin production and secretion, ultimately leading to hyperglycemia, a hallmark of diabetes." (PMID 39347352, 2024). "For any DR, both algorithms identified 6 risk factors (insulin use, HbA1c%, duration of diabetes, random blood glucose, age, and PP) and 2 metabolites (tyrosine and alanine)." (PMID 38546730, 2024). "Insulin was invented over a hundred years ago, and insulin therapy plays an important role in the treatment of subjects with diabetes who have absolute or relative insulin deficiency." (PMID 39629047, 2024). "Drawing from the literature reports cited, it is posited that a correlation exists between reduced eGFR and heightened susceptibility to diabetes, reduced insulin sensitivity, elevated insulin levels, and amplified B-cell function." (PMID 38388456, 2024). "Diabetes Mellitus is a metabolic disease characterized by elevated blood sugar levels caused by inadequate insulin production, which subsequently leads to hyperglycemia." (PMID 38565861, 2024). "People on insulin treatment or with a longer duration of diabetes have been shown to be at higher risk of developing diabetic retinopathy from uncontrolled diabetes." (PMID 39587498, 2024). "On the one hand, Puerarin can increase serum insulin and lower blood sugar levels, thereby reducing the occurrence of diabetes caused by STZ." (PMID 39758348, 2024). "For instance, higher levels of indole propionic acid, produced by intestinal microbes, correlated with improved insulin sensitivity and a lowered risk of T2D onset in the Finnish Diabetes Prevention Study." (PMID 38294727, 2024). "Diabetes mellitus is a serious metabolic disorder caused by the abnormality of carbohydrate metabolism, which is linked to low blood insulin levels or the insensitivity of target organs to insulin." (PMID 38794476, 2024). "Diabetes mellitus is a metabolic disease characterized by chronic hyperglycemia due to a deficiency in insulin secretion or an increase in insulin resistance." (PMID 38297165, 2024). "TXNIP-mediated redox inhibition was associated with the premature death of insulin-secreting cells in patients with diabetes." (PMID 38397668, 2024). "The American Diabetes Association (ADA) defines Diabetes Mellitus (DM) as a group of metabolic diseases characterized by hyperglycaemia resulting from defects in insulin secretion, insulin action, or both." (PMID 38771888, 2024). "Our study was also conceived to address insulin need and IR throughout a hypocaloric intervention with oat-days as proposed by the guideline of the German diabetes association." (PMID 39274338, 2024). "Diabetes mellitus (DM) is a persistent metabolic condition marked by elevated blood glucose levels due to either an insufficient amount of insulin, insulin resistance caused by dysfunctional cells, or a combination of both factors." (PMID 38558585, 2024). "The likely reason for this association is prolonged diabetes can decrease insulin hormone production by the pancreas or result in target cell resistance." (PMID 38820429, 2024).
diabetes (continued). "Protein glycosylation plays a critical role in regulating insulin secretion and is intricately linked to diabetes and its various complications." (PMID 39355507, 2024). "Increasing evidence indicates that disruptions in sleep architecture are linked to impaired glucose homeostasis, reduced insulin secretion, and a heightened risk of diabetes." (PMID 39597994, 2024). "Type 2 diabetes mellitus is commonly associated with obesity, a condition that can exacerbate insulin resistance, impairing the ability to utilize insulin effectively." (PMID 38681576, 2024). "The triglycerides to Apolipoprotein A1 ratio (TG/APOA1) holds promise to be a more valuable index of insulin resistance for the diagnosis of metabolic dysfunction-associated fatty liver disease (MAFLD) in type 2 diabetes mellitus (T2DM)." (PMID 39764250, 2024). "The presence of diabetes, use of insulin, or glucose variability were mentioned as potential risk factors for falls inside the hospital." (PMID 38413865, 2024). "Diabetes mellitus is a group of metabolic disorders characterized by hyperglycemia caused by insufficient insulin secretion, weak peripheral insulin action, or both." (PMID 38702769, 2024). "Obesity, particularly abdominal obesity, is associated with resistance to the action of insulin on peripheral glucose and fatty acid use, often leading to type 2 diabetes mellitus." (PMID 38885005, 2024). "We identified significant associations with type 2 diabetes mellitus, hypertension, hypertensive heart disease, long-term (current) use of insulin and oral hypoglycaemics, hyperlipidaemia, hypercholesterolaemia, liver disease, and ASCVD." (PMID 38918595, 2024). "Regarding diabetes management factors, the present study revealed significant associations between the use of oral hypoglycemic medications and insulin injections and higher adherence to SMBG." (PMID 39188431, 2024). "Monogenic defects of beta cell function refer to a group of rare disorders that are characterized by early-onset diabetes mellitus due to a single gene mutation affecting insulin secretion." (PMID 39408828, 2024). "Type 1 diabetes mellitus (T1DM) is a chronic condition caused by an inability of the pancreas to produce insulin and requires lifelong insulin therapy." (PMID 38194257, 2024). "MDH2 has also been shown to play a critical role in insulin secretion, and mutations in this gene are known to cause diabetes." (PMID 39324112, 2024). "For example, many patients are often taken off their outpatient medications and placed on insulin during hospitalization in line with current American Diabetes Association (ADA) recommendations." (PMID 39835258, 2024). "All the articles that were included examined the effect of incorporating the FII to predict insulin response or how it is linked to diabetes or insulin resistance development or management." (PMID 38474713, 2024). "Diabetes mellitus, a particularly common endocrine illness, causes blood sugar levels to rise either because beta cells aren't producing enough insulin (Type 1) or the insulin that is generated is rendered useless (Type 2)." (PMID 38090734, 2024). "Women who necessitate oral hypoglycemic drugs or insulin to manage their GDM are also at higher risk for postpartum diabetes." (PMID 39807452, 2024). "Although not directly linked, they interact with multiple genes associated with diabetes, obesity, and insulin secretion." (PMID 39273144, 2024). "Diabetes mellitus (DM) is characterized by inherited or acquired deficiency in the production of insulin by the pancreas or by the ineffectiveness of insulin produced." (PMID 38496103, 2024). "Diabetes mellitus, characterized by impaired insulin signaling, is associated with increased incidence and severity of infections." (PMID 38526063, 2024). "Diabetes mellitus is a disease of carbohydrate metabolism disorders caused by the failure of the pancreas gland to produce the hormone insulin." (PMID 37425387, 2023).